PECAM1 (platelet and endothelial cell adhesion molecule 1)
Diseases named in the same sentence as PECAM1 in open-access papers (continued):
Sharing a sentence is not in itself a finding about the gene and the disease.
cancer (426 papers, 1998 to 2026). A tumor composed of atypical neoplastic, often pleomorphic cells that invade other tissues. "Stromal cells (or cancer-associated cells) included endothelial cells (PECAM1/CD31+ and MMRN1+), fibroblasts (COL6A1+, COL1A1+, THY1+, and DCN+), epithelial cells (LAMC2+, KRT5+, and KRT14+), and unassigned name cells (high heat shock proteins expression), suggesting that they were cancerous cells." (PMID 35742914, 2022). "In the cancer group only, differences in marker concentrations between serum and cystic fluid were observed for sIL-6Ra, sVEGFR-2, PECAM-1, and SCF." (PMID 40940878, 2025). "This study showed PECAM1 is underexpressed in LUAD compared to normal lung tissues, and the underexpression was linked to poorer cancer prognosis." (PMID 40563443, 2025). "By using markers of specific clusters, we identified five distinct cell types, including cancer‐associated fibroblasts (CAFs) (COL1A1), endothelial cells (PECAM1), epithelial cells (CDH1), immune cells (PTPRC), and neurons (RELN)." (PMID 40038875, 2025). "We identified three major stromal cell types, including cancer-associated fibroblasts (CAFS; FAP, COL1A1), perivascular-like cells (PVL; PDGFRA, PDGFRB), and endothelial cells (PECAM1, CD34)." (PMID 40858992, 2025). "PECAM1 expression was closely associated with other well-established TAE markers such as CDH5 (R = 0.94) and TIE1 (R = 0.93) in cancer str of the CRC tumors." (PMID 38557819, 2024). "Here we demonstrate that platelet-endothelial cell adhesion molecule 1 (PECAM-1) internalization drives β-catenin-mediated endothelial-mesenchymal transition (EndMT) to link DM to cancer." (PMID 37580771, 2023). "In this study, we illustrated that PECAM-1 drives β-catenin-mediated EndMT via internalization in CCs with DM, a crucial mechanism linking DM to cancer." (PMID 37580771, 2023). "The results indicated that SPP1 is a cancer promoter (oncogene), while PECAM1 and PIK3R1 are cancer suppressor genes." (PMID 36688087, 2023). "Cancer cells take advantage of these molecules on the platelet surface to form platelet–cancer cell conjugates through carbohydrate–protein recognition by P-selectin, protein bridging (e.g., by fibrinogen) between integrins as well as PECAM-1–integrin binding." (PMID 35409226, 2022). "At the intersection between cancer cells and vasculature, we observed bright PECAM-1+ spots that indicated broken or open vascular ends." (PMID 34754042, 2021). "PECAM-1 is a marker for endothelial cells and its expression has been found in several types of human cancers." (PMID 31344919, 2019). "For other cell adhesion molecules, such as CECAM-1 or PECAM-1, similar involvement in cancer cell metastasis was described." (PMID 28903388, 2017). "We accurately monitored the capability of the cancer cells to adhere to the blood vessels by fluorescently labeling the vasculature with an anti‐Pecam1 antibody." (PMID 28694244, 2017). "Gene expression was normalised to both flotillin-2 (per cell expression level) and PECAM-1 (per endothelial cell expression level) in order to assess the level of enrichment of the target in the cancer endothelium." (PMID 26943033, 2016). "The pixel intensity of PECAM‐1 staining surrounding cancer cells in blood vessels was higher around RhoC‐depleted cells compared to control cells at 10 min after cell injection." (PMID 25677806, 2015). "From these clusters, five major cell types were identified via classical cell markers, including T cells (CD3E, CD8A, CD3D), B cells (CD19, MS4A1, CD79A), myeloid cells (CD14, CD68, LYZ), endothelial cells (PECAM1, VWF, CDH5) and cancer-associated fibroblasts (CAFs) (ACTA2, FAP, PDGFRB)." (PMID 39941131, 2025). "For example, the stromal subset consisted of endothelial cells identified by expressions of VWF, PECAM1 and KDR, pericytes with high RGS5, ACTA2, and COL4A1 expressions, and cancer-associated fibroblasts (CAFs) identified by significant expressions of COL1A1, DCN and LUM." (PMID 38925650, 2024).
cancer (continued). "The scientific rationale behind the targeted interaction of pEV with cancer cells lies in the vast range of surface receptors and glycoproteins, such as platelet P-selectin (CD62p), GPIIb/IIIa, or PECAM-1 (platelet-endothelial cell adhesion molecule-1), present on the surface of pEV." (PMID 36986815, 2023). "In this study, PECAM-1 was also expressed in CC cells, which maybe modulate cancer cell growth and metastasis, being parallel with the report." (PMID 37580771, 2023). "For example, ADT levels of EPCAM on cancer/epithelial cells (c0, c4, c8, c14 and c15), CD31 (PECAM1) and CD34 on endothelial cells (c7 and c9), CD146 (MCAM) on perivascular cells (c11), CD90 (THY1) and CD34 on CAFs (c13) and CD45 (PTPRC) on immune cells (c3, c5 and c12)." (PMID 33971952, 2021). "Either way, the strength of our work is validated by the fact that we could observe elevation in previously reported cancer-specific biomarkers in specific cancers, such as G-CSF, GM-CSF, IL-10, and PECAM-1 (seeTable 1 for HC to cancer differences)." (PMID 33108394, 2020). "In hematological malignancies, PECAM1 also acts as a cancer promoter." (PMID 29938007, 2018). "PECAM-1 surface expression plays a role in cancer cell growth and metastasis." (PMID 20074345, 2010). "We then checked the expression of the canonical cell-type markers: cancer/epithelial cell marker genes (Cdh1, Krt18, and Krt5); mesenchymal cell marker genes (Col1a1, Col1a2, and Col3a1); immune cell marker genes (Ptprc, Cd68, and Csf1r); and endothelial cell marker genes (Pecam1, Emcn, and Cdh5)." (PMID 34497807, 2021). "We found a positive correlation between ENH and PECAM1 expression levels in LUAD and other malignant tumors." (PMID 40536254, 2025). "These included, but were not limited to: PECAM1 and CDH5 (EC markers), PDGFRA (fibroblast marker), PDGFRB (pericyte marker), and EPCAM and KRT18 (cancer cell markers)." (PMID 38183074, 2024). "PECAM1 and PRDM1 immune gene expression was negatively related to the non-cancer recurrence-adjusted radiomic features of LHH_glszm_LGLZE and LHH_ngtdm_Contrast." (PMID 35454802, 2022). "Subsequently, we performed FACS detection of CAMs, and the results showed that cancer group cells had increased CD18 (ITGB2), CD106 (VCAM-1), and CD31 (PECAM-1), with decreased CD54 (ICAM-1)." (PMID 28350008, 2017). "Cell adhesion molecules such as ICAM, B1 integrin, P-selectin, PECAM-1, CXCL12 and SDF-1 may also contribute to carcinoma metastases." (PMID 36497364, 2022). "To verify this hypothesis, we examined the changes in the behaviors of the cancer cells when MMP-9, PDGFR-α, and PECAM-1 (CD31) were blocked in vitro and in vivo." (PMID 30483898, 2019). "Moreover, in IDC paths #1 and #2, marker genes for endothelial cells (VWF and PECAM1), lymphocytes (CD4), macrophages (CD68), chemokines (CXCL12 and CCL5), and chemokine receptors (CXCR4) were expressed highly at the intermediate stages of cancer progression." (PMID 39965034, 2025). "Given that adhesive intercellular contacts are crucial for the regulation of microvascular function, which includes vascular permeability and the transendothelial migration of cancer cells, we confirmed that PMP could modify the levels of adhesion proteins VE‐cadherin, PECAM-1 and ZO-1 in ECs." (PMID 40713559, 2025). "Indeed, tension exerted by a neutrophil through PECAM-1 is required for its successful TEM and this might be relevant in cancer cell TEM, too." (PMID 39457016, 2024). "On the other hand the serum levels of ADIPOQ, CXCL9, PECAM-1, Prolactin, sVEGFR-1 and sVEGFR-2 in the T2D-HCC patients were higher than those of patients with only T2D while they were similar to those of HCC patients, confirming that these proteins are specific for the cancer presence." (PMID 26226632, 2015). "Importantly, our method also identified pathways that were not previously considered to be universally disrupted in cancers, such as the Adherens Junction and PECAM1 pathways." (PMID 23822816, 2013).
cancer (continued). "The non-immune cells included endothelial cells (PVALP and PECAM1), CAFs (COL1A1 and COL1A2), and cancer cells (KRT18 and VEGFA)." (PMID 38216635, 2024).
infection (89 papers, 2008 to 2025). The state of being infected such as from the introduction of a foreign agent such as serum, vaccine, antigenic substance or organism. "PECAM-1 is an endothelial cell surface protein known to act as a receptor for pneumococci adhesion to the endothelium and to be upregulated upon infection and stimulation by pathogen-associated molecules (45, -, 47)." (PMID 37358300, 2023). "qRT-PCR analysis also showed that the angiogenesis-related genes, Angpt1, Id1, and Lyve1, were significantly upregulated at 10 weeks post-infection, and Pecam1 was significantly upregulated at 10–12 weeks post-infection." (PMID 41334166, 2025). "Vascular cells shared six down-regulated DEGs in response to either Aβ pathology or MA10 infection, (Rgs5, Slc1a2, Flt1, Sparcl1, Bsg, Pecam1)." (PMID 41497643, 2025). "Next, PECAM-1 immunofluorescence was compared across genotypes and after Ac2-26 treatment during infection." (PMID 39768195, 2024). "The non-infected brain slices displayed very weak immunofluorescence staining for PECAM-1, while the strongest increase was detected 48 h after infection." (PMID 39768195, 2024). "An increase in PECAM-1 during infection can increase bacterial load in the brain, supporting infection progression, as shown in previous studies." (PMID 39768195, 2024). "In contrast, PECAM-1 cell surface abundance was significantly (P < 0.001) decreased following infection with whole-cell W83 and W83-derived OMVs compared to both untreated controls and the ΔK/R-ab equivalents." (PMID 32726180, 2020). "Infection induced PECAM-1 expression on the mesenteric vascular endothelium of infected diabetic (DN315) and non-diabetic (CN315) rats, whereas the molecule was barely detectable in tissues from control group animals (Cs and Ds)." (PMID 30705678, 2018). "Functionally, there are patchy deficiencies in vascular barrier integrity following infection, with a spatial distribution that closely matches the clustering of CLDN5 and PECAM1, as revealed by extravasation of Sulfo-NHS-biotin, a low molecular weight intravascular tracer." (PMID 37318981, 2023). "The mesenteric expression of PECAM-1 was increased after infection with the N315 HLA+ strain." (PMID 30705678, 2018). "The level of PECAM-1 declined at day 1 post-infection and then gradually increased." (PMID 28824565, 2017). "Infection with HBV results in upregulation of PECAM-1 mRNA in PBMCs." (PMID 29699354, 2014). "Infection led to a decrease in PECAM-1 signal in FPR1-KO mice, but Ac2-26 treatment significantly increased PECAM-1 immunofluorescence in infected FPR1-KO mice (p < 0.01)." (PMID 39768195, 2024). "We also found that the protein levels of PECAM-1 and VE-cadherin were decreased after ATCC 33277 infection compared with the levels in the BHI group." (PMID 37199607, 2023). "In leptomeninges flatmounts, infection produces mislocalization and clustering of CLDN5 and PECAM1, disorganized capillary morphology, and an expansion of the area covered by capillaries." (PMID 37318981, 2023). "Junctional proteins including JAM, PECAM-1 and CD99 are activated by ROS during infection and bind the leukocyte ligands such as MAC-1, leading to vascular permeability." (PMID 34025711, 2021). "Upon infection with wild-type P. gingivalis, but not the ΔK/R-ab mutant, we observed a marked reduction in PECAM-1 or VE-cadherin fluorescence accompanied by increased dextran leakage in the caudal vein, further underscoring the contribution of gingipains to vascular damage." (PMID 41310669, 2025). "In diabetic rats (DATCC), infection resulted in the expression of ICAM-1 and P-selectin, but not of PECAM-1, and insulin treatment did not alter this pattern." (PMID 30705678, 2018). "However, the protein levels of PECAM-1 and VE-cadherin did not change significantly after strain KDP 136 infection." (PMID 37199607, 2023).
cardiovascular disease (14 papers, 2014 to 2025). "Literature review revealed that SELP and PECAM1 are associated with angiogenesis and cardiovascular diseases, while CXCR4, IL2RG, and CD48 are primarily involved in immune responses." (PMID 40612110, 2025). "Among these, SELP and PECAM1 were mainly expressed in endothelial cells and are involved in angiogenesis and cardiovascular disease." (PMID 40612110, 2025). "OMVs can also increase vascular permeability and promote cardiovascular disease, which may be related to the mechanism of proteolysis of endothelial cell adhesin molecules (such as PECAM-1)." (PMID 40843171, 2025). "Based on the DEG between IS etiologies and its association with cardiovascular diseases in previous studies, we selected three over-represented genes in EVs for further validation; namely, IGFBP-2 and PECAM-1 increased in EVs from CE patients, and NECTIN-2 overexpressed in AT patients." (PMID 38673963, 2024). "PECAM1 rs9303470 has not been previously associated with cardiovascular disease related outcomes, but other variants in PECAM1 have been found to be associated with CAD." (PMID 33171725, 2020). "Furthermore, the key genes identified by MCODE analysis, HP, CXCL12, COL3A1, and PECAM1, may also serve as candidate targets for cardiovascular disease diagnosis." (PMID 32612856, 2020).
heart disease (3 papers, 2017 to 2024). "Through big data analysis, we found that HBP family members, such as HP, CXCL12, COL3A1, PECAM1, and other highly correlated genes, play a role in heart diseases." (PMID 32612856, 2020).
hematologic malignancies (3 papers, 2018 to 2025). "A previous review indicated that platelet endothelial cell adhesion molecule-1 (PECAM-1/CD31) is involved in inhibiting apoptosis and thus contributes to resistance to chemotherapeutic treatment in various types of tumors, including hematologic malignancies." (PMID 38560563, 2024).
PECAM1 also shares sentences with these, for which no sentence is quoted: hemangioma (44 papers); prostate carcinoma (30); epithelioid angiosarcoma (23); brain tumor (19); liver cancer (18); sarcoma (18); cervical carcinoma (17); Kaposi's sarcoma (17); lymphangioma (17); adenocarcinoma (16); prostate tumors (14); liver fibrosis (13); emphysema (12); preeclampsia (12); colitis (11); keloid (11); neuroblastoma (11); renal cell carcinoma (11); adenoma (10); colorectal tumors (10); lymph node metastasis (9); lymphopenia (9); myxoma (9); ovarian tumors (9); bladder cancer (8); cyst (8); gastric tumor (8); mesothelioma (8); renal fibrosis (8); cerebral infarction (7).
A further 420 diseases each share a sentence with PECAM1 in 7 papers or fewer.